ENSG00000307331 (novel transcript)
Gene: Long non-coding RNA gene on chromosome 2 (42,810,544 to 42,940,488, forward strand). Ensembl gene ENSG00000307331.
Gene Ontology:
Molecular function: triplet codon-amino acid adaptor activity
Biological process: translation